APC (APC regulator of Wnt signaling pathway)
Diseases named in the same sentence as APC in open-access papers (continued):
Sharing a sentence is not in itself a finding about the gene and the disease.
Astrocytomas (4 papers, 2004 to 2025). "Large deletions of the APC gene associated with increased β-catenin levels, together with oncogenic effects of both β-catenin and GSK3β, are clearly involved in astrocytoma evolution." (PMID 34064046, 2021). "Astrocytomas with changes of APC had higher H-score values of total β-catenin compared to the group without genetic changes (t = −2.264, p = 0.038)." (PMID 34064046, 2021). "In the present study, we investigated genetic and epigenetic changes and protein expression levels of negative regulators of Wnt signaling, DKK1, DKK3, and APC as well as glycogen synthase kinase 3 (GSK3β) and β-catenin in 64 human astrocytomas of grades II–IV." (PMID 34064046, 2021). "Seventeen genes (ABL, APC, APAF1, BRCA1, CSPG2, DAPK1, hMLH1, LKB1, PTEN, p14ARF, p15INK4b, p27KIP1, p57KIP2, RASSF1C, RB1, SURVIVIN, and VHL) displayed a uniformly unmethylated pattern in all the astrocytoma and non-astrocytoma tissues examined." (PMID 15367334, 2004). "In this study, 64 astrocytoma samples of grades II–IV were analyzed for genetic and epigenetic changes as well as protein expression patterns in order to explore the roles of the Wnt pathway components, such as DKK1, DKK3, GSK3β, β-catenin, and APC in astrocytoma initiation and progression." (PMID 34064046, 2021). "A recent report has found an increase of promoter hypermethylation in CALCA and CDH1 genes in high-grade astrocytomas, but they did not see any remarkable methylation frequency of other classical tumor suppressor genes, such as p14ARF, RB1, CDKN2B, or APC." (PMID 22389839, 2012).
celiac disease (4 papers, 2015 to 2025). An autoimmune genetic disorder with an unknown pattern of inheritance that primarily affects the digestive tract. "As APC mutations occur exclusively in small-bowel cancer patients without IBD and celiac disease, this may strongly affect our findings as no patients of IBD or celiac disease were observed in our study." (PMID 34014970, 2021).
cutaneous melanoma (4 papers, 2018 to 2022). A primary melanoma arising from atypical melanocytes in the skin. "We examined the prognostic significance of somatic APC/CTNNB1 mutations in the Cancer Genome Atlas Project for Skin Cutaneous Melanoma (TCGA-SKCM) database." (PMID 34986841, 2022). "To investigate whether the presence of somatic mutations in APC/CTNNB1 genes is a prognostic factor in cutaneous melanoma, we performed OS analysis on the TCGA SKCM cohort." (PMID 34986841, 2022).
cyst (4 papers, 2020 to 2025). A sac-like closed membranous structure that may be empty or contain fluid or amorphous material. "We have previously shown that FAP-hESCs carrying APC truncation mutations (FAP1 and FAP2) generated only a few cyst-like structures and cell aggregates of various shapes, while FAP3 generated complex and molecularly mature three-dimensional colonic structures." (PMID 40695959, 2025). "During cystoblast/cyst divisions, activity of CRL4 and APC/C are very high at the 4- and 8-cell cyst stages, delaying cell cycle timing." (PMID 32117961, 2020).
endometrioid ovarian cancer (4 papers, 2020 to 2025). "The aberrant activation of the APC/b-catenin pathway is suggested to be restricted to endometrioid ovarian cancer." (PMID 32766142, 2020).
Ewing sarcoma (4 papers, 2014 to 2025). A small round cell tumor that lacks morphologic, immunohistochemical, and electron microscopic evidence of neuroectodermal differentiation. "ML111 induces a pro-metaphase arrest of Ewing’s sarcoma cells that may be associated with context-dependent inhibition of the APC/C complex, which harbors ubiquitin E3 ligase activity." (PMID 34683845, 2021). "Using a highly stringent selection criteria (a β difference of <0.5), four unique genes (GDF, OSM, APC and HOXA11) were selected that were the most significantly differentially-methylated genes in the Ewing’s sarcoma samples." (PMID 25202378, 2014). "The methylation of these top four genes was confirmed to be common, occurring in 82.5% (GDF), 65% (OSM), 87.5% (APC) and 45% (HOXA11) of the Ewing’s sarcoma samples." (PMID 25202378, 2014). "Thus, four unique genes (GDF10, OSM, APC, and HOXA11) were selected that were the most significantly differentially methylated in the Ewing’s sarcoma samples." (PMID 25202378, 2014).
fibromatosis (4 papers, 2009 to 2017). A poorly circumscribed neoplasm arising from the soft tissues. "The deep fibromatosis is suggested to have somatic β-catenin or APC gene mutations causing increased intranuclear accumulation of β-catenin that may result in proliferation of cells." (PMID 28819469, 2017). "In addition, SAMD9 expression was dramatically increased in an aggressive fibromatosis tumor with inactivation of the APC gene after transfection of wild type APC." (PMID 19691856, 2009).
Hereditary breast and ovarian cancer syndrome (4 papers, 2004 to 2024). An autosomal dominant inherited syndrome caused by mutations in the BRCA1 or BRCA2 genes. "His mother (with AJ ancestry) subsequently had genetic testing from GeneDx Laboratory for the 20 gene breast ovarian cancer panel with the APC gene added on and was found to have the AJ APC founder mutation (c.3920T>A)." (PMID 30152102, 2018).
hereditary diffuse gastric cancer (4 papers, 2016 to 2024). "Familial diffuse gastric cancer and hereditary diffuse gastric cancer are the most recognizable, familial gastric cancer caused by APC, CDH1, and CTNNA1 gene mutations, respectively." (PMID 38649672, 2024).
hypercoagulability (4 papers, 2015 to 2022). "It has also been shown that there is a statistically significant difference between IBD patients and controls in thrombocyte volume, protein C, protein S, APC resistance, F1+F2 fragments, and tPA, which are associated with hypercoagulability." (PMID 35631302, 2022). "Maternal thrombophilia—apart from APS—consisted in most cases of APC resistance, Faktor V Leiden mutation." (PMID 31510056, 2019). "A single point mutation in the factor V Leiden (G1691A) that specifically converts amino acid at 3 sites (most importantly arginine 506 to glutamine) leads to an inability of APC to cleave factor V (the mutant is strongly resistant to APC) and thus to a hypercoagulable state." (PMID 26247037, 2015).
myeloid neoplasm (4 papers, 2011 to 2020). Proliferation of myeloid cells originating from a primitive stem cell. "We also found somatic mutation of APC (5q22) as initial event in del(5q) case, a role for low expression of APC in the pathogenesis of myeloid neoplasms." (PMID 28031539, 2017). "Following evidence that activated β-catenin signaling in the BM niche is a driving force of myeloid neoplasms, the antihelminthic drug pyrvinium was used to inhibit increased microenvironmental β-catenin signaling in the adenomatous polyposis coli (APC) haploinsufficiency mouse model of MDS." (PMID 32630305, 2020).
oral squamous cell carcinoma (4 papers, 2011 to 2024). "Elevated CDC20 expression in oral squamous cell carcinoma cells causes premature anaphase due to disrupted APC activity, leading to genomic instability, including aneuploidy." (PMID 39795587, 2024). "Other biomarkers of the Wnt cascade, E-cadherin, vimentin, Adenomatous polyposis coli (APC), Snail and N-cadherin were revealed to be of importance in the carcinogenesis of other cancer types, such as oral squamous cell carcinoma." (PMID 35873564, 2022). "Our aim was to analyze ATM and APC methylation and its relationship with oral squamous cell carcinoma (OSCC)." (PMID 22414247, 2011).
pancreatic adenocarcinoma (4 papers, 2016 to 2024). "According to all or most algorithms, low APC expression enhanced the immune infiltration capacity of CD8+ T-cells in ACC, UCEC, pancreatic adenocarcinoma, and uveal melanoma." (PMID 35303016, 2022). "A panel of hypermethylated genes (BMP3, RASSF1A, BNC1, MESTv2, TFPI2, APC, SFRP1 and SFRP2) are able to differentiate between patients with pancreatic adenocarcinoma and a most relevant control group." (PMID 27891190, 2016). "We developed a diagnostic prediction model (age >65, BMP3, RASSF1A, BNC1, MESTv2, TFPI2, APC, SFRP1 and SFRP2), which was able to differentiate between pancreatic adenocarcinoma and a large control group of great clinical relevance." (PMID 27891190, 2016). "Pancreatic adenocarcinoma (67.5%) was the most prevalent digestive adenocarcinoma without APC alteration but with KRAS alteration." (PMID 38672586, 2024). "The rates of digestive adenocarcinoma without APC, KRAS, and CDKN2A alterations in patients with biliary tract, gastric, colorectal, and pancreatic adenocarcinomas were 54.8%, 21.0%, 18.5%, and 5.6%, respectively." (PMID 38672586, 2024).
parathyroid adenomas (4 papers, 2010 to 2023). "Subsequent APC analyses on HRPT2 mutated parathyroid adenomas with loss of parafibromin expression have shown that APC is uniformly expressed in these tumours, thereby demonstrating a superior specificity which potentially could be of clinical use." (PMID 21197463, 2010). "This presents a credible explanation to the fact that parathyroid adenomas display retained APC protein expression as demonstrated in previous publications although possibly endowed with APC promoter 1A hypermethylation." (PMID 20208994, 2010). "RASSF1A promoter hypermethylation led to diminished RASSF1A mRNA levels in parathyroid adenomas as compared to normal parathyroid tissues, whereas APC gene expression is retained through augmented expression of APC 1B mRNA regulated by APC promoter 1B." (PMID 20208994, 2010). "For the total levels of APC mRNA, all 16 parathyroid adenomas available for qRT-PCR exhibited greater relative expression levels compared to the normal parathyroid mean, ranging from 1.3–9 (normal parathyroid mean = 1) and a mean relative expression of 4.5." (PMID 20208994, 2010). "In this study, we have determined the levels of promoter methylation regarding the four tumour suppressor genes APC, RASSF1A, p16INK4A and RAR-β in parathyroid adenomas." (PMID 20208994, 2010). "In this study we demonstrate frequent hypermethylation of the APC and RASSF1A tumour suppressor genes in the majority of parathyroid adenomas." (PMID 20208994, 2010). "For the two cases with germ-line HRPT2 gene mutations (H1-2), the atypical adenoma case H1 presented with virtually no methylation (2.3%), whereas the parathyroid adenoma H2 was endowed with the highest density of APC methylation in the entire series (77.5%)." (PMID 20208994, 2010). "It is not known whether the hypermethylation of APC promoter 1A bears any pathological consequences to parathyroid growth, since APC protein expression has been previously demonstrated in parathyroid adenomas." (PMID 20208994, 2010).
parathyroid carcinomas (4 papers, 2010 to 2022). "Shortly after parafibromin was coupled to the Wnt pathway, investigations of Wnt regulators detected widespread loss of APC immunoreactivity in most parathyroid carcinomas—which has later been coupled to promoter hypermethylation in PCs." (PMID 33269427, 2021). "The WNT/β-catenin signaling pathway was aberrantly activated in the analyzed parathyroid carcinomas, due to lost expression of APC likely caused by promoter DNA methylation." (PMID 21078161, 2010). "In parathyroid carcinomas specifically, loss of APC protein expression is a frequent event, and this could in part be due to aberrant methylation patterns rather than gene mutations." (PMID 33269427, 2021). "In two publications, the APC expression in parathyroid carcinoma was found to be statistically significantly decreased." (PMID 35805976, 2022). "Aberrant immunophenotype is characterised by a set of markers that are lost (parafibromin), down-regulated (e.g., APC protein, p27 protein, calcium-sensing receptor) or up-regulated (e.g., proliferation activity by Ki-67 exceeding 5%) in parathyroid carcinoma compared to benign parathyroid disease." (PMID 35805976, 2022).
pilomatricoma (4 papers, 2016 to 2021). "Moreover, the mutation in APC-pathway can take part in pilomatrixoma development." (PMID 33946233, 2021). "Additionally, the mutation in APC-pathway can take part in pilomatrixoma development." (PMID 33946233, 2021). "The WNT/APC/β-catenin pathway regulates hair follicle development, hair follicle cycling, and hair growth and β-catenin is strongly expressed in the proliferating matrix cells of pilomatricoma, both in catenin-β mutated tumors and in pilomatricomas without a CTNNB1 mutation." (PMID 32155193, 2020).
prostate tumors (4 papers, 2013 to 2025). "Consistent with this, recent exome sequencing has shown that members of the WNT pathway, including APC, are frequently mutated in aggressive prostate tumours, and these cancers are enriched for mutations in a PTEN interacting network." (PMID 23300485, 2013). "The APC promoter was shown to be hypermethylated in prostate tumors with a sensitivity of 64%–90% and a specificity of 91%–96%." (PMID 39783747, 2025). "APC promoter methylation exists at high levels in prostate tumors and is a poor prognosis indicator in prostate cancer." (PMID 35715489, 2022). "In a panel of three genes, methylation of GSTP1, APC, and MDR1 in prostate tumors was significantly associated with pathological stage (p < 0.001), Gleason score (p < 0.001), capsular involvement (p < 0.001), vesicle invasion (p = 0.002), and pelvic lymph node metastasis (p = 0.001)." (PMID 39783747, 2025).
rectal polyps (4 papers, 2018 to 2025). "Typically, IRA is recommended for individuals with a mild polyposis phenotype—fewer than 20 rectal polyps and fewer than 1000 colonic polyps—which goes along with a genotype where the APC pathogenic variant is outside the mutation cluster region." (PMID 40911204, 2025). "Factors associated with rectal failure from these studies include APC pathogenic variants in the mutation cluster region, greater than 20 rectal polyps or greater than 500 colon polyps at the time of surgery, and rectal polyps with high-grade dysplasia." (PMID 40911204, 2025). "While the sire was unavailable for evaluation of the APC genotype, a littermate full sister (dog F) of dog E was referred for treatment of a rectal polyp and tested positive for the APC variant." (PMID 37505844, 2023).
thymoma (4 papers, 2007 to 2022). A neoplasm arising from the epithelial cells of the thymus. "Although the molecular genetics of human thymomas are largely unclear, the presence of APC mutations has been linked to pathogenesis of type B3 thymomas." (PMID 26101855, 2015). "Previous molecular genetic studies have identified loss of heterozygosity (LOH) at the adenomatous polyposis coli (APC) locus was associated with the type B thymomas." (PMID 26101855, 2015). "For patients with types A and B1/B2 thymoma (n = 9), seven gene mutations, including MTOR, BRCA1, APC, NF1, HRAS, NTRK3, and PTCH1, were detected, and each gene appeared only once in patients with non-TCs+type B3 TETs." (PMID 34307137, 2021). "Also, LOH at APC locus has been found in the type B thymomas." (PMID 26101855, 2015).
thyroid tumor (4 papers, 2017 to 2025). A benign or malignant neoplasm affecting the thyroid gland. "Previous studies indicated that enhanced Wnt signaling is a later event in the development of thyroid tumor, because the most frequent genetic mutations in Wnt signaling genes APC, Axin or β-catenin were found in later stage poorly differentiated and ATC, instead of PTC." (PMID 28570681, 2017). "In multicentric thyroid tumors of FAP patients, it has been found that each tumor has a different somatic APC mutation (second hit), suggesting an independent development of each tumor through biallelic inactivation of the APC gene." (PMID 33495912, 2021). "Rare somatic mutations in thyroid tumors such as in the KMT2C and KMT2D genes have been described in 1 and 4 cases of C-MV of TC, respectively, coexisting with the germline mutation of the APC gene." (PMID 33495912, 2021).
acinar cell carcinoma (3 papers, 2014 to 2018). "In acinar cell carcinomas, genetic alterations in the Wnt signaling pathway have been shown in four of 17 investigated cases, including three truncating mutations of the APC gene, and one 1-bp missense mutation in codon 41 of exon 3 of the β-catenin gene." (PMID 25009661, 2014).
adrenocortical cancer (3 papers, 2020 to 2022). "Approximately three percent of patients with Familial Adenomatous Polyposis (FAP), caused by mutations in the Adenomatous Polyposis Coli (APC) gene, develop adrenocortical cancer as adults." (PMID 32781574, 2020).